CD226 (CD226 molecule)
Diseases named in the same sentence as CD226 in open-access papers (continued):
Sharing a sentence is not in itself a finding about the gene and the disease.
infection (continued). "We also extended the analysis of HCV-specific CD4+ T cells and compared the TIGIT and CD226 expression of HCV-specific CD4+ versus CD8+ T cells of acutely and chronically versus HCV patients with spontaneous resolution of infection." (PMID 31337800, 2019). "We found that early after infection of primary B cells, EBV promoted an increase in CD226 mRNA and protein expression." (PMID 29202043, 2017). "An absence of CD226 in Ly49H+ NK cells leads to the suppression of expansion capacity and memory generation after infection with mouse Cytomegalovirus (MCMV)." (PMID 36361628, 2022). "Additionally, at different stages of infection, CD96−CD226+ cells among NK cells, TIGIT+NK and TIGIT−NK cells significantly diminished, while CD96+CD226− cells expanded (all P < 0.05)." (PMID 33717085, 2021). "Moreover, evidence was provided that the IRF-1, an IFN-γ-induced transcription factor pivotal in the regulation of infection and inflammation, upregulated TRAIL and DNAM-1/CD226 on NK cells." (PMID 23476104, 2013). "CD96+CD226+ cells among NK cells especially TIGIT+NK cells did not significantly expand at different stages of infection, while these cells among TIGIT−NK cells increased in the first month of infection and in chronic infection over 2 years (all P < 0.05)." (PMID 33717085, 2021).
infectious disease (3 papers, 2020 to 2025). A disorder directly resulting from the presence and activity of a microbial, viral, or parasitic agent in humans. "Some of the molecules analyzed here, such as CD321, GITR, CD226 or CD108, that have shown associations with different parameters of the patient’s evolution have been insufficiently studied in infectious diseases." (PMID 35743356, 2022).
cardiovascular disease (1 paper, 2020). "Inhibition of CD226 may represent a novel therapeutic approach to improve wound repair in the infarcted heart and other cardiovascular disease." (PMID 32104514, 2020).
renal disease (1 paper, 2021). "The results showed that the proportion of CD226+ B cells was higher in patients with renal involvement; this reflected renal disease activity." (PMID 34367178, 2021).
CD226 also shares sentences with these, for which no sentence is quoted: neuroblastoma (16 papers); multiple myeloma (11); graft versus host disease (5); hematological malignancies (4); prostate carcinoma (4); rhabdomyosarcoma (4); acute lymphoblastic leukemia (3); cervical cancer (3); colon carcinoma (3); Ewing sarcoma (3); lung adenocarcinoma (3); myelocytic leukemia (3); ovarian tumor (3); ankylosing spondylitis (2); erythroleukemia (2); kidney (2); lung squamous cell carcinoma (2); myelodysplastic syndrome (2); papilloma (2); abortion (1); adenoma (1); AIDS (1); allergies (1); B-cell lymphoma (1); benign prostatic hyperplasia (1); bladder cancer (1); brain tumor (1); breast tumor (1); celiac disease (1); chronic GVHD (1).
A further 44 diseases each share a sentence with CD226 in 1 paper.